TBX4 (T-box transcription factor 4)
Description:
Transcriptional regulator that has an essential role in the organogenesis of lungs, pelvis, and hindlimbs.
Synonyms: ICPPS; PAPPAS; SPS
Tractability: No criterion of Open Targets' tractability assessment is met for any kind of drug.
Gene: Protein-coding gene on chromosome 17 (61,451,906 to 61,485,110, forward strand). Ensembl gene ENSG00000121075.
Subcellular location: Nucleus
Subcellular location (Human Protein Atlas): Vesicles
Gene Ontology:
Molecular function: DNA binding; DNA-binding transcription factor activity, RNA polymerase II-specific; RNA polymerase II cis-regulatory region sequence-specific DNA binding; DNA-binding transcription factor activity
Biological process: embryonic hindlimb morphogenesis; embryonic lung development; limb morphogenesis; skeletal system morphogenesis; angiogenesis; cell fate specification; regulation of transcription by RNA polymerase II; embryonic limb morphogenesis; positive regulation of DNA-templated transcription; regulation of DNA-templated transcription
Cellular component: chromatin; nucleus
Genetic constraint (gnomAD): Loss-of-function variants: 13 observed, 54.47 expected, observed/expected ratio (o/e) 0.24, 90% interval 0.15 to 0.38. The upper end of that interval is the gene's LOEUF score, 0.38, which puts it in group 1 of 6, group 1 being the genes least tolerant of losing a copy. Missense variants: 631 observed, 732.25 expected, observed/expected ratio (o/e) 0.86, 90% interval 0.81 to 0.92. Synonymous variants: 314 observed, 309.87 expected, observed/expected ratio (o/e) 1.01, 90% interval 0.92 to 1.11.
Gene-disease validity (ClinGen):
ClinGen rates the evidence that TBX4 causes each of these diseases.
pulmonary arterial hypertension (autosomal dominant): Definitive. Pulmonary arterial hypertension (PAH) is a group of diseases characterized by mean pulmonary artery pressure >20 mmHg and elevated pulmonary arterial resistance leading to right heart failure.
Homologues: Orthologues: chimpanzee TBX4 (99% identical), macaque TBX4 (99% identical), rabbit TBX4 (95% identical), dog TBX4 (94% identical), mouse Tbx4 (94% identical), pig TBX4 (94% identical), rat Tbx4 (94% identical), tropical clawed frog tbx4 (83% identical), guinea pig TBX4 (78% identical), zebrafish tbx4 (58% identical), Caenorhabditis elegans mab-9 (23% identical), Drosophila melanogaster mid (23% identical), and 9 more. Paralogues in human: TBX5 (52% identical), MGA (29% identical), TBX2 (29% identical), TBX3 (29% identical), TBX18 (28% identical), TBX15 (27% identical), TBX1 (26% identical), TBX10 (25% identical), TBX22 (25% identical), TBX20 (25% identical), TBX6 (24% identical), TBX21 (23% identical), and 4 more.
Diseases named in the same sentence as TBX4 in open-access papers:
TBX4 is named in the same sentence as 55 diseases in open-access papers, as found by Europe PMC text mining. Sharing a sentence is not in itself a finding about the gene and the disease. The quoted sentences say what the papers report.
small patella syndrome (19 papers, 2016 to 2026). "Dysregulation of TBX4 is implicated in serious diseases, including pulmonary hypertension, small patella syndrome, and tracheal stenosis, with mutations and aberrant expression patterns emerging as potential diagnostic markers." (PMID 41439135, 2026). "Heterozygous TBX4 variants cause the small patella syndrome (also known as the ischiocoxopodopatellar syndrome [ICPPS; OMIM #147891])." (PMID 37623346, 2023). "Intronic variants are also associated with ischiocoxopodopatellar syndrome as well as TBX4-related pulmonary hypertension." (PMID 36878902, 2023). "Less frequent syndromic causes of PAH include ischiocoxopodopatellar syndrome (see TBX4 below) and Adams–Oliver syndrome." (PMID 35772304, 2022). "TBX4 is involved in the regulation of embryonic developmental processes and its haploinsufficiency was classically associated with Small Patella Syndrome." (PMID 34199176, 2021). "Whole exon sequencing (WES) screening demonstrated that T-box 4 (TBX4), a gene linked to small patella syndrome 8, is the most commonly mutated gene in pediatric patients with HPAH along with BMPR2." (PMID 33269111, 2020). "Deletions and LoF mutations in TBX4 cause a variety of developmental lung disorders and have been identified as a prominent risk factor in small patella syndrome (SPS), childhood-onset PAH and more recently, persistent pulmonary hypertension in neonates." (PMID 33256119, 2020). "An interesting candidate mutation in patient DII.1 is the TBX4 variant (p.A246T): this gene has been implicated in small patella syndrome and associated childhood onset pulmonary arterial hypertension." (PMID 29843651, 2018). "Mutations in TBX4 have been previously reported to cause small patella syndrome, an autosomal-dominant skeletal dysplasia characterized by patellar aplasia or hypoplasia." (PMID 27294413, 2016). "In humans, mutations of TBX4 causes Small Patella syndrome, which involves skeletal dysplasia." (PMID 31063509, 2019). "Heterozygous variants in TBX4 were originally associated with the autosomal dominant ischiocoxopodopatellar syndrome (ICPPS; OMIM 147891) or small patella syndrome." (PMID 36085161, 2022). "Small patella syndrome (SPS) is a rare autosomal dominant disorder caused by mutations in TBX4 gene which encodes a transcription factor of FGF10." (PMID 35216193, 2022). "Small patella syndrome, characterized by patellar hypoplasia and abnormalities of the pelvis and the foot, is caused by LMX1B and TBX4 mutations in the PITX1/TBX4 signaling cascade." (PMID 38965548, 2024). "Heterozygous TBX4 variants cause ischiocoxopodopatellar syndrome (ICPPS; OMIM #147891), also known as small patella syndrome, whilst homozygous loss-of-function variants underlie posterior amelia with pelvic and pulmonary hypoplasia syndrome (PAPPAS; OMIM #601360)." (PMID 35772304, 2022). "The most severely affected skeletal elements are also the same as those affected in human ischiocoxopodopatellar syndrome (OMIM: 147891), an autosomal dominant disorder caused by mutation in the TBX4 gene." (PMID 34423345, 2021). "Pathogenic variants in TBX4 are a well-established cause of PAH in children, typically associated with skeletal disorders (small patella syndrome, MIM #147891), intellectual disabilities and other cardiovascular disorders." (PMID 32348326, 2020). "Heterozygous SNVs in TBX4 and CNV deletions involving TBX4 and TBX2 have been reported also in pediatric and adult patients with pulmonary arterial hypertension (PAH), ischiocoxopodopatellar syndrome (MIM# 147891), and developmental delay, heart defects, and limb abnormalities." (PMID 33478486, 2021). "More recently, TBX4-specific likely gene-disrupting (LGD) and damaging missense variants have been associated with PAH with or without small patella syndrome (OMIM #147891), most frequently in pediatric cases." (PMID 33081265, 2020).
small patella syndrome (continued). "Throughout this time his physical examination was notable for retractions with exercise, lung fields clear to auscultation, and widely spaced first and second toes that is typically observed in TBX4-related ischiocoxopodopatellar syndrome with or without pulmonary arterial hypertension." (PMID 36878902, 2023).
pulmonary arterial hypertension (14 papers, 2016 to 2026). "In summary, we describe a family with two siblings affected by severe pulmonary hypertension and diffuse lung disease who carry a TBX4 variant from the father." (PMID 36878902, 2023). "Herein, we present the clinical phenotype and prognosis of all Pulmonary Arterial Hypertension patients with disease-associated variants in TBX4." (PMID 32348326, 2020). "TBX4-associated Pulmonary Arterial Hypertension has marked clinical heterogeneity." (PMID 32348326, 2020). "In summary, it is biologically plausible that rs6557421 variant in Nox3 and rs3744439 variant in Tbx4 may have potential effects on individual susceptibility to pulmonary hypertension, which could lead to therapeutic or diagnosis approaches in PH." (PMID 30290780, 2018). "The results suggested that rs6557421 variant in Nox3 and rs3744439 variant in Tbx4 might have potential effect on individual susceptibility to pulmonary hypertension, which could lead to therapeutic or diagnosis approaches in PH." (PMID 30290780, 2018). "Canonical pulmonary arterial hypertension genes such as BMPR2, KCNK3, and TBX4 are well described, but novel associations continue to emerge." (PMID 41133550, 2025). "In fact, TBX4 is regarded as being in charge of the developmental lung problems connected to pulmonary hypertension, according to the most recent update on pediatric pulmonary hypertension." (PMID 38443964, 2024). "According to the pulmonary hypertension gene curation expert panel of pulmonary hypertension of ClinGen, the association of BMPR2, KCNK3, KDR, SMAD9, and TBX4 and PH is definitive, GDF2 is strong, and AQP1 has a limited disease relationship." (PMID 35627312, 2022). "In addition, TBX4 mutation can lead to childhood onset pulmonary arterial hypertension (PAH) with common clinical features including pulmonary capillary dysplasia, acinar dysplasia, respiratory failure, and in severe cases, death." (PMID 35216193, 2022). "TBX4 is associated with autosomal dominant ischio-coxo-podo-patellar syndrome with/without pulmonary arterial hypertension (ICPPS, #147891), reaching a diagnosis in the family." (PMID 39467966, 2025). "We suggest including TBX4 in genetic studies of neonates with pulmonary hypertension, even in the absence of skeletal abnormalities." (PMID 38443964, 2024).
clubfoot (10 papers, 2018 to 2026). The most common congenital deformation of the foot, occurring in 1 of 1,000 live births. "Our study aimed to evaluate the prevalence of pathogenic variants in PITX1 and TBX4 in Italian patients with idiopathic clubfoot." (PMID 36360195, 2022). "To identify the PITX1 and TBX4 mutations responsible for clubfoot, we sequenced all the coding regions and exon-intron boundaries of 162 patients’ samples." (PMID 36360195, 2022). "TBX4 and other clubfoot susceptibility genes increase predisposition to clubfoot in human males; variation in penetrance can be caused by their modifier(s) with sex-biased expression(s), resulting in different expression patterns in males versus females." (PMID 31443640, 2019). "Here, we mainly discussed SPS, DDH, and clubfoot, which have been confirmed to be the most relevant to TBX4." (PMID 41439135, 2026). "The dysregulation of TBX4 has been implicated in various human limb disorders such as SPS, DDH, and clubfoot." (PMID 41439135, 2026). "Initially, genes associatedwith clubfoot (PITX1, TBX4, HOXA9, HOXD10, HOXD12,HOXD13, HOXA9, TPM1, TPM2, COL9A1, FLNB, CASP8,CASP10, UTX, CHD1, RIPPLY2, CAND2, WNT7) werescreened for potential variants." (PMID 38952703, 2024). "Our data proved that the idiopathic form of congenital clubfoot was rarely associated with mutations and CNVs on PITX1 and TBX4." (PMID 36360195, 2022). "Additionally, TBX4 has been implicated in DDH and congenital clubfoot, reinforcing its importance in skeletal development and joint formation." (PMID 41439135, 2026). "TBX4, a direct target of PITX1, has been linked to the pathogenesis of clubfoot." (PMID 40746736, 2025). "Therefore, further investigation is required to elucidate the involvement of TBX4 in the pathogenesis of isolated clubfoot, which seems to present as a syndromic phenotype." (PMID 40746736, 2025). "TBX4 microdeletions and microduplications have been reported in patients affected by ICTEV, suggesting that chromosome 17q23.1q23.2 microduplication is a relatively common cause of familial isolated clubfoot." (PMID 30134936, 2018). "It has been reported that the development of clubfoot involves various genes, such as PITX1, HOXD9, and TBX4, thereby emphasizing the intricate nature of genetic contributions to this condition." (PMID 38858754, 2024). "Several studies support the evidence of the crucial role of PITX1 (MIM 602149) and TBX4 (MIM 601719) genes in early limb development and clubfoot aetiology." (PMID 36360195, 2022). "Although no major gene in clubfoot etiopathogenesis has been identified, variants in the genes PITX1 and TBX4 have been intensively studied, but without consistent results." (PMID 38929227, 2024).
lung fibrosis (10 papers, 2013 to 2024). "TBX4 plays a role in lung development and has been linked to pulmonary fibrosis, suggesting a possible role in PAH; nonetheless, experimental evidence is required to confirm this." (PMID 33256119, 2020). "In mouse models, specific knockout of TBX4 or perturbation of TBX4 gene function in fibroblasts markedly relieved lung fibrosis after bleomycin-induced damage." (PMID 34869721, 2021). "TBX4 belongs to the ancient T-box family of transcription factors that drives the accumulation of myofibroblasts and the development of pulmonary fibrosis." (PMID 34869721, 2021). "It has been shown to induce myofibroblast proliferation and drive invasion of the matrix by fibroblasts, promoting the development of pulmonary fibrosis, and deletion of Tbx4 has led to a reduction in fibrosis." (PMID 33256119, 2020). "TBX4 is a mesenchymal transcription factor that drives the accumulation of myofibroblasts and the development of pulmonary fibrosis." (PMID 31311130, 2019). "TBX4 is a member of the T-box genes that is important for the development of airway branching and the regulation of lung fibrosis." (PMID 31382961, 2019). "Tbx4 was also regarded as a mesenchymal transcription factor that drove myofibroblasts accumulation and the development of lung fibrosis." (PMID 30290780, 2018). "Recently, TBX4 was found to play an important role in lung fibrosis in mice via its actions in αSMA+ myofibroblasts and COL1α1+ fibroblasts." (PMID 30081553, 2018). "Other genes activated in CF-HLF as in lung fibrosis were: TBX4 and ITGA8." (PMID 32492951, 2020). "Therefore, our Tbx4-lung enhancer driven targeting driver line has the potential to be used in the study of adult lung diseases, such as asthma, emphysema and interstitial pulmonary fibrosis." (PMID 24225400, 2013). "At the same time, they overexpressed genes of the WNT pathway, TBX4, and ITGA8, which have been demonstrated to play a part in lung fibrosis." (PMID 32492951, 2020). "However, at the exception of TBX4 and PRRX1, the expression of all these other TFs is not restricted to mesenchymal lineages, which means that targeting those TFs may impact both lung fibrosis and epithelial regeneration/repair." (PMID 37261432, 2023).
lung carcinoma (9 papers, 2016 to 2026). "In lung cancer, TBX4 exhibits a hypermethylated state, and in lung adenocarcinoma, specific TBX4 methylation patterns are associated with pathogenesis and tumor-suppressive effects." (PMID 41439135, 2026). "High-throughput sequencing technology analysis in lung fibroblasts suggested that TBX4 in lung cancer associated fibroblasts (CAFs) was downregulated and highly methylated." (PMID 38413457, 2024). "TBX4 was associated with tumor stage of lung cancer, similar to the result in PDC." (PMID 38413457, 2024). "Since other studies suggest that TBX4 is downregulated and hypermethylated in lung cancer-associated fibroblasts and cancers, we speculated that TTTY15 may participate in the methylation status of the TBX4 promoter." (PMID 31311130, 2019). "Furthermore, TBX4 has been shown to have decreased expression in human lung cancer associated fibroblasts in comparison to matched normal lung fibroblasts, providing preliminary support that TBX4 expression may be involved in FP biology." (PMID 33717164, 2021). "Similar to the result of Horie M, our data showed that the expression of TBX4 in lung cancer tissues showed a significant decrease compared to normal tissues." (PMID 38413457, 2024). "It indicated that epigenetic silence of TBX4 was involved in phenotypic alteration of CAFs from lung cancer." (PMID 38413457, 2024). "TBX4, which is involved in the regulation of embryonic developmental processes, is downregulated in lung cancer, and it was decreased in all sets of the long-term treatment group." (PMID 35354498, 2022). "In our study, we found that TTTY15 was downregulated in lung cancer and was mainly located in the nucleus, upregulating TBX4 expression by targeting DNMT3A." (PMID 31311130, 2019). "TBX4 hypermethylation has been observed in bladder cancer and lung cancer." (PMID 37760434, 2023). "For instance, in lung we found FOXA2, TBX4 and BMP4, and although the role of LHX6 in lung development is less well defined, it has previously been implicated as a tumour suppressor in lung cancer." (PMID 27562343, 2016). "Besides, low expression of TBX4 predicted poor prognosis of lung cancer patients." (PMID 38413457, 2024). "However, MYBL2 is only co-expressed in lung cancer microarray CCP, TBX4 is only co-expressed in lung cancer RNA-Seq CCP, PKNOX2 is not co-expressed in any CCP, and neither is a regulator in the GRNs." (PMID 36661515, 2023). "Moreover, the lung cancer-specific OS rate significantly increased in patients with TBX2 subfamily high expression group than that in low expression group (TBX2 logrank P = 0.0023, TBX3 logrank P = 1.9e-5, TBX4 logrank P = 0.027, TBX5 logrank P = 2.2e−10)." (PMID 38413457, 2024). "Two of the most frequently dysregulated transcription factors are co-expressed in lung cancer and PAH (FOXM1 and FOXF1), while the other six frequently deregulated transcription factors are co-expressed only in lung cancer (TCF21, SOX17, TAL1, LMO2, KLF2, and TBX4)." (PMID 36661515, 2023). "Moreover, FOXF1 is also co-expressed in the CCP of the LC RNA-Seq datasets, along with seven of the most frequently dysregulated TFs (FOXM1, SOX17, TAL1, TCF21, TBX4, LMO2, and KLF2), suggesting its importance as a regulator of gene expression during lung cancer progression." (PMID 36661515, 2023).
lung disease (6 papers, 2020 to 2026). "Heterozygous TBX4 variants are the second most common genetic cause of pediatric pulmonary hypertension (PH), yet mechanisms underlying TBX4-related lung disease remain poorly understood." (PMID 42044173, 2026). "A sequencing panel of genes associated with heritable pulmonary disorders gave a normal result; however, a chromosomal microarray identified a heterozygous deletion encompassing the TBX4 gene on chromosome 17." (PMID 40008593, 2025). "The most plausible interpretation is that the patient suffers from hereditable PAH associated with a TBX4 variant and probable parenchyma lung disease." (PMID 32348326, 2020). "TBX4’s role in the lung developmental microenvironment is also associated with other lung diseases." (PMID 41439135, 2026). "From the review of the literature, it appears that the clinical picture associated with TBX4 variants found in neonatal cases is severe, with PH requiring advanced medical therapy and a poor respiratory outcome, due to a severe lung disease, in those who survived." (PMID 38443964, 2024). "In recent years, TBX4 has also been suggested as pathogenetic for pulmonary disease." (PMID 38443964, 2024).